LINC02584 (long independently transcribed non-coding RNA 2584)
Synonyms: formerly C11orf78; NCRNA00224; ANO1-AS2
Gene: Long non-coding RNA gene on chromosome 11 (70,072,065 to 70,085,346, reverse strand). Ensembl gene ENSG00000254417.
Gene Ontology:
Molecular function: U4 snRNA binding
Biological process: formation of quadruple SL/U4/U5/U6 snRNP; spliceosomal tri-snRNP complex assembly
Cellular component: U4/U6 x U5 tri-snRNP complex; U6 snRNP
Diseases named in the same sentence as LINC02584 in open-access papers:
LINC02584 is named in the same sentence as 1 disease in open-access papers, as found by Europe PMC text mining. Sharing a sentence is not in itself a finding about the gene and the disease.
LINC02584 shares sentences with these, for which no sentence is quoted: cancer (1 paper).